APOE (apolipoprotein E)
Diseases named in the same sentence as APOE in open-access papers (continued):
Sharing a sentence is not in itself a finding about the gene and the disease.
atherosclerosis (continued). "Blockade of sympathetic tone by propranolol (8 mg/kg), a non-specific β-blocker, resulted in higher bradycardic in WT mice compared to ApoE−/− mice on RD suggesting that sympathetic tone is exacerbated in this mouse model of atherosclerosis." (PMID 19823587, 2009). "We investigated the association between intraperitoneal injection of pristine C60 fullerenes and vasomotor dysfunction in the aorta of 11–13 and 40–42 weeks old apolipoprotein E knockout mice (apoE-/-) with different degree of atherosclerosis." (PMID 19243580, 2009). "Another study reported that ciprofibrate treatment in ApoE knockout mice promoted the progression of atherosclerosis." (PMID 19636418, 2009). "Treatment with C60 fullerenes affected mainly the response to vasorelaxation in young apoE-/- mice, whereas the vasomotor dysfunction in old apoE-/- mice with more advanced atherosclerosis was less affected by acute C60 fullerene treatment." (PMID 19243580, 2009). "Very recent data showed that sEH inhibitors attenuate the progression of renal damage in diabetic GK rats from Taconic and also the development of atherosclerosis in apolipoprotein-E-knockout mice." (PMID 19742300, 2009). "Experimental animal work using hypercholesterolemic rabbits and apoE null mice shows that ambient PM exposure promotes atherosclerosis and that the smaller the particles, the greater the proatherogenic effects." (PMID 19761620, 2009). "We have previously shown that PDZK1 confers protection against aortic root atherosclerosis in apoE KO mice fed an atherogenic, Western-type, high fat/high cholesterol diet for 3 months." (PMID 19956623, 2009). "The primary aim of the study was to investigate the effect of C60 fullerenes at different stages of atherosclerosis by using apoE-/- mice with different age." (PMID 19243580, 2009). "PDZK1 has been shown to be atheroprotective using the high fat/high cholesterol (‘Western’) diet-fed murine apolipoprotein E (apoE) KO model of atherosclerosis, presumably because of its role in promoting reverse cholesterol transport via SR-BI." (PMID 19956623, 2009). "In contrast, genetic deletion of PPARα in ApoE knockout mice resulted in more severe atherosclerosis." (PMID 19636418, 2009). "We have shown that systemic exposure to diesel exhaust particles by intraperitoneal (i.p.)injection reduced acetylcholine-elicited vasorelaxation in apoE-/- mice with minimum atherosclerosis, whereas opposite effects were seen in wild type mice." (PMID 19243580, 2009). "By contrast, Claudel andcolleagues demonstrated that treatment with the dual PPARα/γ compound,GW2331, for 11 weeks was more effective at attenuating atherosclerosis infemale apoE KO mice than rosiglitazone alone." (PMID 18288280, 2008). "Administration of PCB-77 to ApoE−/− mice increased atherosclerosis in aortic root sections (0.002 μm2 mean lesion area in PCB-77− injected mice; nondetectable in vehicle controls; p = 0.032)." (PMID 18560532, 2008). "Genetic deficiency of TLR2 reduces diet- and/or pathogen-associated atherosclerosis in ApoE+/− mice, along with differences in plaque composition suggesting greater structural stability while TLR-2 ligand-specific activation triggers atherosclerosis." (PMID 18787704, 2008). "Our expression proteomic approach extends the growing body of literature linking TLR2 and atherogenesis by identifying proteins involved in P. g- and/or diet-induced atherosclerosis in ApoE+/− mice." (PMID 18787704, 2008). "Taken together, our results confirm the important role for TLR2 signaling in diet and/or bacteria enhanced atherosclerosis in an ApoE+/− mouse model, providing a link between innate immunity, inflammation and atherosclerosis." (PMID 18787704, 2008).
atherosclerosis (continued). "To find the in vivo relevance of these data we have analyzed the effect of atorvastatin in an experimental model of atherosclerosis that has been widely reported to be representative (the ApoE-/- mice model)." (PMID 19088845, 2008). "ApoE KO mice develop hypercholesterolemia and atherosclerosis that closely resemble the human conditions and are rapidly reversed when APOE protein is supplied." (PMID 18464897, 2008). "Our data showing elevated levels of plasma MCP-1 in asbestos-exposed ApoE−/− mice are consistent with growing evidence that cytokines participate as autocrine and paracrine mediators in the pathogenesis of atherosclerosis." (PMID 18795166, 2008). "Male apoE knockout (apoE-/-) mice fed on a diet containing 1.25% cholesterol (wt/wt) were divided into pravastatin group provided with pravastatin (80 mg kg-1 per day) and atherosclerosis group." (PMID 19330073, 2008). "A typical example would be association between polymorphisms in the apolipoprotein E (APOE), cholesteryl ester transfer protein CETP, stromelysin-1 and β-fibrinogen with progression of atherosclerosis, cardiovascular events and death." (PMID 20040945, 2008). "The results demonstrated reversible switching of ApoE transcription, plasma cholesterol levels, and atherosclerosis progression and regression." (PMID 18464897, 2008). "Further, serum cholesterol, atherosclerosis, apolipoprotein-E and AD all appear to be interconnected." (PMID 18691432, 2008). "Even with the production of 3% of wild-type level of ApoE protein, the hypercholesterolemia and atherosclerosis phenotypes of the ApoE KO mice can be reversed." (PMID 18464897, 2008). "As others and we have previously observed, there is a fairly wide variation in the amount of atherosclerosis detected in apoE−/− mice." (PMID 18560564, 2008). "Consistently, atherosclerosis was accelerated in SWCNT-exposed ApoE−/− mice primed with a high-fat diet." (PMID 17431486, 2007). "They found that old ApoE deficient mice had suffered from exhaustive consumption of their EPC and this had promoted development of atherosclerosis by deficient vascular repair mechanism." (PMID 17925881, 2007). "A mouse model of atherosclerosis (ApoE−/−) was exposed to either filtered air or concentrated FPM (CAPs) in Tuxedo, New York (85 μg/m3 average, 6 hr/day, 5 days/week, for 6 months), and the FPM elemental composition was determined for each day." (PMID 17107850, 2006). "In this study, we determined the effects of glucose and glucosamine on endothelial cells and SMCs in vitro and on atherosclerosis in apoE null mice." (PMID 16207378, 2005). "Notably, targeting the sno-circCNOT1-LMNA-METTL14-NLRP3 axis attenuates atherosclerosis in ApoE−/− mice, highlighting its therapeutic potential." (PMID 41510160, 2026). "In this regard, the ApoE atherosclerosis/cardiac fibrosis models offer a robust platform for the potential development of PACAP‐biased agonists, which may offer benefit in multiple aspects of cardiac disease." (PMID 41292235, 2026). "These in vivo results validate that R@MLP can effectively treat atherosclerosis in ApoE−/− mice." (PMID 41035425, 2026). "Furthermore, we have reported that imeglimin shows beneficial effects on the progression of atherosclerosis in STZ-induced diabetic ApoE KO mice, independently of glycolipid metabolism." (PMID 41585322, 2026). "Cerebral amyloid angiopathy exhibited a striking ε4 dose-response (OR = 5.76, 95% CI: 4.20-7.96, p < 0.001; for ε4/ε4 compared to ε3/ε3), whereas arteriolosclerosis and atherosclerosis risk increased with age, independent of APOE haplotype." (PMID 41890856, 2026). "Additionally, activation of the Nrf2 signaling cascade in ApoE−/− mice inhibits ferroptosis in macrophages, thereby reducing oxidative stress and inflammatory responses and alleviating atherosclerosis." (PMID 40861271, 2025). "ApoE−/− mice lacking systemic AnxA8 (ApoE−/−AnxA8−/−) were generated to assess the effect of AnxA8 deficiency on atherosclerosis." (PMID 39835780, 2025).
atherosclerosis (continued). "In this study, ApoE−/− mice were fed with high-fat diets for eight weeks to induce atherosclerosis." (PMID 40537740, 2025). "Moreover, the suppression of IL-17 in the apoE-deficient mice affected the IL-4 and IFN-γ values, resulting in the reduction of the atherosclerosis process." (PMID 40823653, 2025). "ApoE‐mimetic peptides have been shown to reduce inflammation in models of atherosclerosis." (PMID 40542610, 2025). "Furthermore, it has been reported that the transgenic introduction of sclerostin in ApoE−/− (SOSTTg.ApoE−/−) mice and the administration of recombinant sclerostin inhibited AngII-induced AA and atherosclerosis development." (PMID 40429697, 2025). "Since hyperlipidemia is necessary for the development of atherogenesis, we adopted ApoE-deficient mice for the present study, since wild-type mice are not hyperlipidemic and do not develop atherosclerosis." (PMID 39851526, 2025). "Atherosclerosis was induced in ApoE‐/‐ mice using a high‐fat diet." (PMID 40856260, 2025). "The APOE locus is a well‐established determinant of plasma lipoprotein profiles; ε4 is associated with elevated LDL, increased oxidation susceptibility, and heightened atherosclerosis risk in the general population." (PMID 40365738, 2025). "This paradoxical phenomenon may arise because foam cells in atherosclerotic lesions of ApoE-/- mice predominantly originate from VSMCs, whereas SMCs constitute at least 50% of foam cells in human atherosclerosis." (PMID 41268556, 2025). "The atherosclerosis model was induced in ApoE-/- mice by feeding Western diet for 12 weeks." (PMID 40577270, 2025). "Moreover, interventions using the ferroptosis inhibitor ferrostatin-1 (Fer-1) or targeting FABP3 can alleviate PGPC-induced ferroptosis in ECs, improve endothelial function and mitigate atherosclerosis in ApoE−/− mice." (PMID 40861271, 2025). "Hence, we utilized the ApoE−/− mouse model to evaluate the effect of exogenous CTRP9 on atherosclerosis." (PMID 38600398, 2025). "Furthermore, F. nucleatum has been demonstrated to accelerate aortic inflammation and atherosclerosis in the aorta of ApoE-null mice." (PMID 41459155, 2025). "ApoE−/− mice fed an HF diet for 8 weeks develop early-stage atherosclerosis." (PMID 40003949, 2025). "Furthermore, after treatment with Citri grandis extract, the levels of TC, TG, and LDL-C significantly decreased in the atherosclerosis model apoE−/− mice after 16 weeks, and aortic plaque, lipid deposition, and endothelial injury were obviously ameliorated." (PMID 41464973, 2025). "Early-stage atherosclerosis in ApoE−/− mice typically develops in the aortic root and aortic arch." (PMID 40003949, 2025). "In ApoE and Tc deficient mice models of atherosclerosis, no changes were observed in the progression of atherosclerosis." (PMID 39944697, 2025). "PCSK9 activates PKCδ, Syk and NF-κB, promoting atherosclerosis progression independently of LDL-R.In apoE-/- mice, the inactivation of PCSK9 has been shown to effectively suppress vascular inflammation and atherosclerosis by reducing the TLR4/NF-κB signaling pathway." (PMID 40354375, 2025). "Depletion of AEP from APOE–/– mice attenuates atherosclerosis." (PMID 40371638, 2025). "Furthermore, aldose reductase (AR) in this pathway contributes to diabetic complications; its overexpression in ApoE knockout mice with diabetes hastens atherosclerosis, whereas pharmacological inhibition of AR alleviates disease progression." (PMID 40149704, 2025).
atherosclerosis (continued). "Furthermore, hepatic Jak2 deletion in male ApoE or LDL receptor-null mice also led to accelerated atherosclerosis." (PMID 40825505, 2025). "Also, preclinical studies employing animal models like ApoE−/− mice receiving microbiota transplants from TMAO-producing mice exhibit heightened atherosclerosis, an effect that decreases when plasma TMAO is reduced." (PMID 40741383, 2025). "Given that metabolic abnormalities such as diabetes and obesity are known risk factors for CVD, we assessed metabolic parameters which may have contributed to the increased atherosclerosis in ApoE−/−P-Jak2 KO mice." (PMID 40825505, 2025). "Specifically, a study suggested that blocking the TP receptor could help treat accelerated atherosclerosis in diabetic patients, showing a greater impact in diabetic apoE−/− mice, which nearly reversed the processes speeding up atherosclerosis." (PMID 41516038, 2025). "Here, we aimed to investigate the efficacy of SerBut dosed through drinking water in a murine apolipoprotein E–knockout (ApoE–/–) model of atherosclerosis, examining effects on vascular inflammation, plaque formation and composition, systemic metabolic regulation, and HFD-induced liver injury." (PMID 40779455, 2025). "Studies have demonstrated that the absence of eNOS lowers superoxide production in ApoE-deficient mice, suggesting that eNOS uncoupling occurs during atherosclerosis." (PMID 40700116, 2025). "We constructed a model of advanced atherosclerosis using apoE-/- mice." (PMID 40225574, 2025). "Since ICAM-1 expression is elevated on endothelium in the aortas of ApoE−/− mice with atherosclerosis, we utilized the I-domain of LFA-1 (idLFA-1) as a payload to create nanocarriers given that I-domain (id) is responsible for mediating ICAM-1/LFA-1 interactions." (PMID 40630903, 2025). "In contrast, another variant of the APOE gene, APOE2, is associated with lower LDL cholesterol levels and may confer a protective effect against atherosclerosis." (PMID 40739848, 2025). "Next, we examine whether the intestinal barrier function and the progression of atherosclerosis of ApoE‐/‐ T2D mice with WT CR infection can be restored by butyrate administration." (PMID 39807021, 2025). "Therefore, we fed a high-fat diet to apolipoprotein E knockout (ApoE−/−) mice for 18 weeks to establish atherosclerosis model and discovered that apigenin intervention significantly attenuated the atherosclerotic lesions." (PMID 40407263, 2025). "ApoE plays a crucial role in lipoprotein clearance, and individuals carrying the APOE ε4 allele exhibit increased levels of low-density lipoprotein (LDL) cholesterol and total cholesterol, predisposing them to atherosclerosis and coronary artery disease." (PMID 40671162, 2025). "Furthermore, in another study, ApoE-/- mice with defective CD40-TRAF6 signaling exhibit attenuated atherosclerosis." (PMID 41268556, 2025). "A very low ApoE circulating concentration in humans was related to early-onset atherosclerosis." (PMID 40429697, 2025). "Next, to verify whether restoring intestinal barrier function can abolish the progression of atherosclerosis in T3SS‐induced ApoE‐/‐ T2D mice, we intervened with butyrate, an intestinal barrier protector." (PMID 39807021, 2025). "Consequently, the APOE*3-Leiden mouse model is valuable for experimental investigations of atherosclerosis, particularly when preservation of Apo E function and assessment of clinical lipid-lowering drug efficacy are required." (PMID 41516253, 2025).
atherosclerosis (continued). "In addition, the transplantation of PVAT from high-cholesterol diet-fed apolipoprotein E knockout (ApoE−/−) mice to normal control diet-fed ApoE−/− mice resulted in a significant increase in atherosclerosis development." (PMID 40514684, 2025). "Finally, over-expression TAL1 specifically in endothelial cells decreased inflammatory response and progression of atherosclerosis in ApoE-/- mice fed with western diet." (PMID 40598260, 2025). "In addition to examining the vascular tissue distribution of the SHep‐EV group in an atherosclerosis model (ApoE−/‐ mice), we used a Hep‐EV tracer mouse to examine the tissue distribution of the EVs." (PMID 39680681, 2025). "PCSK9nb therefore delayed the development of atherosclerosis in ApoE−/− mice." (PMID 41244340, 2025). "Consistently, immunofluorescence staining confirmed elevated CD36 expression in aortic plaques from ApoE−/−EP4MKO mice compared to ApoE−/−EP4Flox mice, suggesting EP4 deficiency exacerbates atherosclerosis through CD36-mediated inflammatory and metabolic dysregulation." (PMID 40643540, 2025). "When the ApoE gene is knocked out, these mice develop impaired lipid metabolism, which leads to a significant increase in blood cholesterol levels, particularly low‐density lipoprotein cholesterol (LDL‐C), a known risk factor for atherosclerosis." (PMID 40718724, 2025). "To establish the presence of ICAM-1 in atherosclerotic lesions in our experimental animal model, we conducted immunofluorescence analysis (IFA) to examine the expression of ICAM-1 on luminal endothelium in the aortas of 22-week-old ApoE−/− mice fed with HFD to recapitulate atherosclerosis." (PMID 40630903, 2025). "It is also important to note that young mice (6–7 weeks of age) were exclusively used for in vivo infections in this study to exclude the confounding effects of atherosclerosis that spontaneously develops in ApoE-/- mice by 3 months of age, even when maintained on a standard chow diet." (PMID 40439406, 2025). "In ApoE–/– mice fed with a Western diet, remdesivir greatly attenuated atherosclerosis progression." (PMID 40598260, 2025). "Importantly, macrophages, which express and upregulate apoE during atherosclerosis, play critical roles in regulating vascular inflammation and lipid homeostasis." (PMID 40275327, 2025). "The interaction between ACE2 and APOE suggests that these proteins may collaborate to modulate lipid metabolism and vascular inflammation, potentially influencing the development of atherosclerosis." (PMID 40142959, 2025). "To investigate Ninj1’s role in atherosclerosis, we synthesized mPN12, a competitive inhibitory peptide targeting Ninj1’s adhesion domain (Pro26-Asn37) and evaluated its effects on plaque development in ApoE−/− mice." (PMID 41280941, 2025). "ORO staining was used to determine the anti-atherosclerosis effects of CGE on HFD-fed apoE−/− mice." (PMID 41464973, 2025). "Curiously, treatment of ApoE-/- mice with antibodies to collagen VI reduced atherosclerosis, but its exact role has remained unknown." (PMID 41025959, 2025). "However, it is shown that IF, although effective in preventing diet-induced obesity, fails to significantly reduce atherosclerotic plaque burden in the aortas of ApoE−/− mice, indicating a potentially limited role of IF alone in atherosclerosis prevention." (PMID 40861271, 2025). "Furthermore, the stability of Nrf2 and suppression of NLRP3 are associated with the atheroprotective action of dong quai meconin in ApoE-/- mice, highlighting its potential as a therapeutic agent for atherosclerosis." (PMID 40099271, 2025).